MYH7 (myosin heavy chain 7)
Diseases named in the same sentence as MYH7 in open-access papers (continued):
Sharing a sentence is not in itself a finding about the gene and the disease.
heart failure (continued). "Although TEAD-1 knockout mice show embryonic lethality, mice in which TEAD-1 was conditionally overexpressed in cardiomyocytes exhibited heart failure with increased MYH7 gene expression." (PMID 24781449, 2014). "We found an upregulation of MYH7 in Stx12‐cKO mice, providing extra evidence of heart failure." (PMID 40568929, 2025). "Moreover, mRNA levels of heart failure markers (Anp, Bnp, and Myh7) were markedly elevated in DOX‐treated AAV‐shEBBP mice compared to DOX‐treated AAV‐shNC controls." (PMID 40491313, 2025). "In contrast, pathological remodelling is characterised by a pronounced transcriptional shift: MYH6 mRNA is significantly downregulated to just a few percent of total myosin transcripts, while MYH7 mRNA increases to nearly 100%, particularly in end-stage heart failure." (PMID 41295372, 2025). "It has been shown that Omecamtiv mecarbil (OM), a selective small-molecule activator of cardiac myosin (MYH7) that was initially developed as a treatment for heart failure, increases submaximal force production in type 1 skeletal muscles of Neb cKO mouse model and rat diaphragm." (PMID 38634969, 2024). "Moreover, the expression of the embryonic genes Nppa and Myh7, which are markers of heart failure, was also significantly increased in the DOX group, as detected by real-time PCR." (PMID 39494326, 2024). "Patients with MYH7 R453C mutation typically develop premature clinical symptoms and severe HCM phenotype, such as cardiac remodelling and arrhythmia, significantly increasing the risk of heart failure and sudden death." (PMID 38862020, 2024). "Alternatively, a homeostatic response may maintain cardiac function before the appearance of heart failure symptoms, as suggested by the significant increase in Nppb, Nppa, and Myh7 at 2 weeks, as displayed in the RNA-seq or mass spectrometry analysis." (PMID 38201239, 2023). "Hypertrophy of adult hearts is also associated with Myh6 downregulation and Myh7 induction, returning to a fetal state of MHC expression and thus controlling the expression of MHC may be an attractive approach for heart failure therapy." (PMID 35858921, 2022). "Moreover, a switch involving decreased Myh6 and Serca2a and increased Myh7 and Pln transcripts was reported in conditions of hypertrophy and heart failure." (PMID 34395557, 2021). "Although OM has been developed for heart failure patients, cardiac myosin (Myh7 or β-Myh) is identical to the type I myosin expressed by slow skeletal muscles suggesting that OM might also be effective in skeletal muscle." (PMID 31721788, 2019). "Although OM has been developed as a heart failure drug, the expression of cardiac myosin (Myh7 or β-MHC) in both heart and slow skeletal muscle, predicts that OM is effective in slow skeletal muscle as well, and the findings of the present study clearly bear this out." (PMID 31721788, 2019). "It appears that TH deficiency may accelerate heart failure in SHRs due to the decrease in SERCA2 and increase in MYH7 expression." (PMID 31374823, 2019). "Thus, the transition from MYH6 to MYH7 found in heart failure is thought to be a maladaptive response." (PMID 24781449, 2014). "We hypothesized that the MYH7 Q315R variant alters energy substrate utilization, resulting in metabolic remodeling in the myocardium and contributing to the progression of LVNC and heart failure." (PMID 41237118, 2025). "Thus, TRβ-selective T3 analogs may be applicable for the treatment of heart failure by reducing MYH7 expression." (PMID 24781449, 2014). "After 1 month, the mouse model demonstrated a prolonged and dose-dependent reduction in heart function, in addition to significant increases in expression of the heart failure markers BNP and MYH7 and areas of cardiac fibrosis." (PMID 41110999, 2025). "During heart failure, HNRNPC physically interacts with myocardial ganglion proteins FHL2, PDLIM5, and MYH7 in the heart." (PMID 38916731, 2024).
heart failure (continued). "Measurement of heart failure indicators showed that BNP and MYH7 in the heart muscle of mice in the CAP+DOX group were notably lower than those in the DOX group." (PMID 37916995, 2023). "Additional heart failure markers: ANF, BNP, and Myh7 were also found to be significantly lowered in TAM-CAMCAKT mice compared to controls after 5 months of HFFD (p < 0.05, < 0.01, < 0.0001, < 0.001, < 0.01)." (PMID 37891673, 2023). "In 3 months old mice, Western blot analysis showed that Vps4a protein levels were significantly decreased in Vps4afl/fl Myh6 mice compared to Vps4afl/fl mice, while the expressions of markers for heart failure, such as p-AKT and Myh7, increased." (PMID 37445978, 2023). "Myh7, a fetal gene re-expressed during pathological cardiac remodeling and heart failure, was significantly upregulated by DOX independent of CSS exposure." (PMID 41542045, 2026). "Intriguingly, we observed a drastic decrease in the Myh6/Myh7 ratio but no change in the expression of Nppa, Col1a1, and Postn in cKO hearts at the early stage, consistent with no cardiac fibrosis or heart failure at this time." (PMID 38201239, 2023). "Myh7-related DCM complicationsprincipally manifest as VAs and heart failure." (PMID 39077026, 2023). "In contrast, studies suggest that ventricular MYH7 does not increase as significantly in human heart failure as in rodent models of heart failure, and decreased levels of MYH7 have been observed at the end of heart failure in some clinical studies." (PMID 37284852, 2023). "On the other hand, STAT3 activates the transcription regulator GATA4, thereby upregulating the expression of NPPA, MYH7, and MYH6, which interacted with each other to regulate the structure and function of the sarcomere, resulting in heart failure and arrhythmias." (PMID 36034815, 2022). "Further, RT-qPCR assays on RNAs from the hearts revealed the upregulation of heart-failure genes (Col1, Myh7, and Anf) in fortilinKO-heart mice, but not in fortilinWT-heart mice." (PMID 34689154, 2021). "Moreover, this histological observation was supported by increased expression levels of heart failure markers, such as ANP and BNP, and physio-functional markers, such as Atp2a2, Myh6, and Myh7, which indicate contractility, cardiomyocyte size and LV wall thickness, respectively." (PMID 35008972, 2022). "In addition, absence of upregulation of βMHC (Myh7), a fetal gene program marker of heart failure, in the failing hearts of the Tead1-cKO mice demonstrates requirement of Tead1 for heart failure-associated fetal program increase in βMHC." (PMID 30811446, 2019). "Likewise, the expression of both the B-type natriuretic peptide gene (Bnp) and of Myh6/Myh7 was induced equally in both groups after TAC, clearly demonstrating that these TBC1D10C TG mice are not protected from TAC-induced hypertrophy or heart failure." (PMID 27667030, 2016).
dilated cardiomyopathy (52 papers, 2009 to 2026). Cardiomyopathy which is characterized by dilation and contractile dysfunction of the left and right ventricles. "Hypertrophic and dilated cardiomyopathy causing mutations have been detected mostly in genes of sarcomere proteins such as Mybpc2, Myh7, Tnnt2, Tnnc1, Tnni3, Tpm1, Ttn, Actc1, Myl2, and Myl3." (PMID 38981849, 2024). "Mutations in MYH7 encoding for the β-MyHC are a common cause of hypertrophic or dilated cardiomyopathy, Laing distal myopathy, and MSM." (PMID 37794383, 2023). "A phase 2a study aiming at establishing safety and preliminary efficacy of danicamtiv in patients with primary dilated cardiomyopathy (DCM) due to MYH7 or TTN variants." (PMID 37332581, 2023). "A study from the German population found the association of MYH7 rs121913645 with dilated cardiomyopathy." (PMID 36140722, 2022). "A genome-wide family-based linkage study conducted in the Brazilian population reported the association of MYH7 rs121913642 with dilated cardiomyopathy." (PMID 36140722, 2022). "The second most common disease arising from mutations in the MYH7 gene is dilated cardiomyopathy (DCM)." (PMID 32651905, 2020). "Mutations in MYH7, encoding slow/β-cardiac myosin heavy chain, are an important cause of hypertrophic and dilated cardiomyopathy, as well as skeletal muscle disease." (PMID 33234710, 2020). "In contrast to the low frequency of mutations in MYH1 and MYH2, more than 500 disease-causing point mutations have been described in MYH7, with the majority producing hypertrophic or dilated cardiomyopathy." (PMID 29510741, 2018). "In line with its expression pattern, MYH7 mutations have been reported in association with hypertrophic or dilated cardiomyopathy, skeletal myopathies or a combination of both." (PMID 27519903, 2016). "The MYH7 sarcomere gene allows beta-myosin expression in heart ventricles, with variants associated with hypertrophic and dilated cardiomyopathies, congenital heart diseases, myocarditis, and excessive trabeculation (formerly known as left ventricular noncompaction)." (PMID 38813076, 2024). "We herein describe an Iranian family with an autosomal dominantly inherited pattern of MSM presenting with slowly progressive muscle weakness and dilated cardiomyopathy associated with the MYH7 (NM_000257): c.C1888A: p.Pro630Thr disclosed by whole-exome sequencing." (PMID 37794383, 2023). "MYH7 missense variants (Phe764Lys and Ser532Pro) elevate rates of force development and Mg-ATP binding, a feature of cardiac myofilaments which underlie the development of dilated cardiomyopathy." (PMID 36140722, 2022). "The most frequently mutated genes related to dilated cardiomyopathy (DCM) were TTN, MYH7, NEXN, TNNI3, and SCN5A." (PMID 41341110, 2025). "After the filtration of the WES data, a novel heterozygous missense mutation in exon 16 of the MYH7 (NM_000257): c.C1888A: p.Pro630Thr, was identified, which was probably responsible for MSM with dilated cardiomyopathy in this family." (PMID 37794383, 2023). "Variants of uncertain significance (VUS) were found in 17 cases (eight resuscitated and nine dead) in genes associated with HCM or dilated cardiomyopathy (DCM), such as TTN, TNNT2, MYH6, DSP, ACTN2, CALR3, and MYH7." (PMID 36588553, 2022). "The Ventricles-Enriched MYH7, FHL2, TNNC1 and TNNI3 genes were associated with dilated cardiomyopathy (DCM)." (PMID 34088950, 2021). "Mutations in MYH7 account for about 4% of all DCM, and the analysis here shows that 14% of all the mutations in MYH7 cause dilated cardiomyopathy." (PMID 32651905, 2020). "For example, decreased MYL2 and MYH6 gene expression coincided with increased RYR2, HCN4, CORIN, NPPA, ERBB2, and MYH7 gene expression in hypertrophic and/or dilated cardiomyopathy." (PMID 32804947, 2020). "Although patients with CCM had rare variants in several established dilated cardiomyopathy (DCM) genes (BAG3, LMNA, MYH7, TCAP, TNNT2, and TTN), only variants in TTN, which encodes titin, were significantly increased." (PMID 30987448, 2019).
dilated cardiomyopathy (continued). "Rapid death of these mice was surprising given that mice with fetal Gata4/6 inactivation by Myh7-Cre (also known as MHCβ-Cre) survived normally through the neonatal period and into adulthood, when they died by ~100 days of age from dilated cardiomyopathy." (PMID 26023924, 2015). "Dilated cardiomyopathy (DCM) is characterized by an expanded left ventricle with a thinned ventricular wall and impaired contractility, and is often associated with mutations in sarcomere genes such as TPM1, TNNT2 and MYH7 (Myosin Heavy Chain 7)." (PMID 37509718, 2023). "For example, mutations in JUP, DSP, PKP2, DSG2, DSC2, CTNNA3, CDH2, or PLN (all of them more abundant in LV) predominantly lead to arrhythmogenic right ventricular cardiomyopathy, and mutations in MYH7, HSPB7, NEXN and MYPN (also all more abundant in LV) lead to dilated cardiomyopathy." (PMID 32291283, 2020). "Mutants in Myh7 might be attributed to the development of dilated cardiomyopathy." (PMID 36698951, 2022). "Collectively, these results suggest that in the context of end-stage dilated cardiomyopathy, the transcriptional regulation of MYH6 and MYH7 is uniformly affected, independent of factors such as age or sex." (PMID 41295372, 2025).
distal myopathy (22 papers, 2011 to 2024). Distal myopathy refers to a group of muscle diseases which share the clinical pattern of predominant weakness and atrophy beginning in the feet and/or hands. "P101 was a 3-year-old boy with a hemizygous indel in DMD, associated with Duchenne muscular dystrophy, and a heterozygous missense variant in MYH7, associated with distal myopathy." (PMID 35628876, 2022). "Laing distal myopathy is a rare autosomal dominant inherited distal myopathy caused by mutations of the MYH7 gene affecting mainly the rod region." (PMID 33298082, 2020). "Mutations in MYH7 cause skeletal myopathies such as myosin storage myopathy and Laing early-onset distal myopathy." (PMID 32315303, 2020). "We showed that the corresponding Drosophila MhcK1728del mutant phenotype recapitulated certain muscle morphological phenotypes manifest in Laing distal myopathy patients carrying the K1729del MYH7 mutation." (PMID 33234710, 2020). "Laing (Gowers–Laing) distal myopathy is caused by dominant mutations, usually in the exons 32-36 of the MYH7 gene." (PMID 32456280, 2020). "In-frame deletions of the MYH7 gene made up 3/4 of mutations in our patients, suggesting that these are common mutations of Laing distal myopathy." (PMID 33298082, 2020). "Very recently, we used CRISPR/Cas9 genome engineering to develop the first fly model for Laing distal myopathy to investigate the pathobiological mechanisms of the recurrent K1729del MYH7 mutation." (PMID 33234710, 2020). "This sign has been considered the hallmark of Laing distal myopathy, an early-onset autosomal dominant disease, due to mutations of slow β-myosin heavy chain (MYH7) gene." (PMID 31133047, 2019). "A minority of MYH7 mutations are reported to cause skeletal myopathies such as myosin storage myopathies or Laing distal myopathy." (PMID 29510741, 2018). "The families analyzed in this study show phenotypic similarity to MPD1, a progressive distal myopathy caused by MYH7 rod mutations." (PMID 27519903, 2016). "We describe the clinical and myoimaging data collected in a family with an autosomal dominant (AD) distal myopathy due to a heterozygous mutation in MYH7, which was initially unrecognized due to incorrect attribution of the phenotype to a variant in RYR1." (PMID 27005958, 2016). "Laing distal myopathy was first linked to chromosome 14q11, and it was later demonstrated to be caused by mutations in MYH7." (PMID 22918376, 2013). "Most patients reported with Laing distal myopathy have dominant mutations in MYH7 located in exon 32-36 in the mid region of the MyHC rod including: R1500P, E1508del, L1591P, A1603P, K1617del, A1663P, L1706P and K1729del." (PMID 22918376, 2013). "Furthermore, mutations in the MYH7 gene can potentially disrupt interactions between myosin and titin with myomesin, M-protein, or sarcomeric structures, leading to Laing Early-Onset Distal Myopathy (MPD1) and tibial muscular dystrophy." (PMID 39280835, 2024). "One exception is the isolated distal lower limb involvement, predominantly of the anterior compartment, seen in around 12% of patients with Laing distal myopathy due to pathogenic MYH7 gene variants, which may mimic the imaging findings seen in NEB‐NM." (PMID 37265148, 2023). "In-frame deletions of the MYH7 gene are common causes of Laing distal myopathy." (PMID 33298082, 2020). "Meanwhile, in-frame deletions of the MYH7 gene are common causes of Laing distal myopathy." (PMID 33298082, 2020). "The “hanging big toe” sign, that is highlighted in an attempt to extend the toes and is due to a selective weakness of the extensor hallucis longus, has been reported in Laing early-onset distal myopathy due to mutations in the slow skeletal muscle fiber myosin heavy chain gene (MYH7)." (PMID 31133047, 2019). "A few patients with MYH7 mutations that otherwise cause distal myopathy could be classified as having limb-girdle syndrome or scapuloperoneal myopathy thus overlapping with the clinical features of myosin storage myopathy." (PMID 22918376, 2013).
distal myopathy (continued). "Although the most important skeletal muscle manifestations of MYH7 mutations are referred to as either myosin storage myopathy or Laing distal myopathy several cases cannot be classified into these groups because they either do not display distal muscle weakness or do not exhibit hyaline bodies." (PMID 22918376, 2013). "Besides familial HCM, DCM and LVNC, Laing early onset distal myopathy and myosin storage myopathy can be caused by MYH7 mutations." (PMID 22194935, 2011). "The restoration of good metrics of muscle physical function and mobility achieved by reprogramming myosin enzymatic activity via oral administration of a small-molecule modulator raises hope for patients with MPD1 and related MYH7 distal myopathies." (PMID 38690726, 2024). "Skeletal myopathies due to MYH7 mutations were initially classified in two main subgroups according to clinical and pathological findings: myosin storage myopathy (MSM, MIM 608358) and Laing distal myopathy (LDM, MIM 160500)." (PMID 27387980, 2016). "Especially MYH7-related skeletal myopathies can be subdivided in two allelic disorders: myosin storage myopathy (OMIM#608358) and Laing early onset distal myopathy (OMIM#160500)." (PMID 32456280, 2020). "However, MYH7-associated distal myopathy is not restricted to mutations in this region." (PMID 22918376, 2013).